LINC01538 (long independently transcribed non-coding RNA 1538)
Synonyms: TCONS_00026184; RP11-909B2.1
Gene: Long non-coding RNA gene on chromosome 18 (64,181,314 to 64,260,055, reverse strand). Ensembl gene ENSG00000266952.
Diseases named in the same sentence as LINC01538 in open-access papers:
LINC01538 is named in the same sentence as 1 disease in open-access papers, as found by Europe PMC text mining. Sharing a sentence is not in itself a finding about the gene and the disease.
LINC01538 shares sentences with these, for which no sentence is quoted: cancer (1 paper).